SNORD37 (small nucleolar RNA, C/D box 37)
Synonyms: U37; RNU37
Gene: Small nucleolar RNA gene on chromosome 19 (3,982,507 to 3,982,572, reverse strand). Ensembl gene ENSG00000206775.
Gene Ontology:
Biological process: RNA processing
Cellular component: nucleolus
Homologues: Orthologues: chimpanzee SNORD37 (94% identical), macaque SNORD37 (94% identical), rat Snord37 (79% identical), pig SNORD37 (77% identical), mouse Snord37 (76% identical).
Diseases named in the same sentence as SNORD37 in open-access papers:
SNORD37 is named in the same sentence as 3 diseases in open-access papers, as found by Europe PMC text mining. Sharing a sentence is not in itself a finding about the gene and the disease. The quoted sentences say what the papers report.
lung carcinoma (1 paper, 2017). "SNORD33 and SNORD37 are located on chromosome 19q13.3 and 19p13.3, respectively that contain potential oncogenes involved in malignancies, including lung cancer 20,57,58." (PMID 29090068, 2017). "Since there is no single validated molecular biomarker for early lung cancer detection and spectrum of biomarkers is needed for early diagnosis, a panel of biomarkers including miR-223, miR-212, miR-3074, miR-192, SNORD33 and SNORD37 were the candidates in our study." (PMID 29090068, 2017).
cancer (1 paper, 2017). A tumor composed of atypical neoplastic, often pleomorphic cells that invade other tissues. "miR-223, miR-212, miR-192, SNORD33 and SNORD37 did not alter in tissue samples of cancer patients compared to non-cancers." (PMID 29090068, 2017).
tumor (1 paper, 2018). "We observed expression of eight snoRNAs from the SNORD116 cluster, and the expression of SNORD37, SNORA10 and SNORA 64 in both tumor and adjacent normal breast tissues." (PMID 29760470, 2018).